GFRAL (GDNF family receptor alpha like)
Diseases named in the same sentence as GFRAL in open-access papers (continued):
Sharing a sentence is not in itself a finding about the gene and the disease.
cancer (continued). "The inhibition of GDF15 activity, by targeting its receptor GDNF family receptor alpha-like (GFRAL) in brainstem neurons of tumor-bearing mice, identified a novel strategy for cancer cachexia treatment." (PMID 33374852, 2020). "In conclusion, we demonstrated that PDAC cells can auto secrete GDF-15 protein, which can directly bind with its membrane receptor GFRAL to promote cancer cell progression." (PMID 33201838, 2020). "Similarly, GFRAL-IR was detected in human normal pancreatic ductal epithelial and cancer cells, which was positively correlated with GDF15 expression." (PMID 38474863, 2024). "Moreover, GDF15 is considered the main actor of cachexia in cancer signaling through its receptor GFRAL." (PMID 37691636, 2023). "However, experimental data indicate that during cancer cachexia, activation of central nervous system pathway (GFRAL–RET) determines the expression of genes involved in adipose tissue wasting." (PMID 34939367, 2022). "Globally, considering both host and cancer factors, only the completion of clinical trials using an inhibitor of the GDF15/GFRAL pathway will provide clinical evidence on the merit of reversing this “metabolic signature” to improve the lives of those living with advanced cancer." (PMID 33442410, 2021). "Therefore, results from ongoing clinical trials in human models inhibiting the GDF15/GFRAL pathway will shed light on patients with cancer cachexia." (PMID 33442410, 2021). "Interestingly, recent studies have also linked RET to alterations in tumor metabolism, an emerging hallmark of cancer, through a novel ligand complex involving Growth Differentiation Factor 15 (GDF15) and the GDNF Family Receptor α-like (GFRAL)." (PMID 30666215, 2018). "Thus, it is unclear whether GFRAL inhibitors, which are being developed and tested to treat cancer anorexia (clinical trial identifier NCT04068896), could be a valid alternative to anti-GDF-15 antibodies for immunotherapy." (PMID 32508832, 2020). "Nevertheless, the expression of GFRAL and GDF15/GFRAL downstream signaling in cancers are yet to be discovered." (PMID 35884930, 2022). "Overall, our findings demonstrated that the GDF-15 secreted by PDAC cells, binds to GFRAL, itself localized in PDAC cells, to promote cancer cell growth and metastasis through the GDF-15/GFRAL signaling pathway." (PMID 33201838, 2020). "Taking together, this study have demonstrated that the GDF-15 secreted by PDAC cells, binds to GFRAL, itself localized in PDAC cells, to promote cancer cell growth and metastasis." (PMID 33201838, 2020). "Given the very limited tissue distribution of GFRAL, direct effects of GDF-15 on cancer or immune cells are likely to be mediated via GFRAL-independent signaling pathways." (PMID 32508832, 2020). "In addition to their potential for treating cancer cachexia, multiple ongoing and planned clinical trials are evaluating GDF-15 and GFRAL inhibitors in combination with ICIs." (PMID 41294666, 2025). "Further mechanistic study reveals that stable MAGEA2-expressing cancer cells highly express GFRAL, while exposure of these cells with CM from Gem treated PSC activate the GFRAL-RET mediated Akt and ERK1/2 dependent cell survival pathway to further enhance their Gem resistance." (PMID 37814317, 2023). "Inhibition of GDF15 activity with antibodies targeting either GDF15 or its receptor GFRAL was found to reverse chemotherapy-induced anorexia and emesis and cancer cachexia in mice and nonhuman primates." (PMID 34831213, 2021). "The caveat to this is that the secretion of GDF15 during cancer, as it appears so for inflammatory infections, is presumably an adaptive response, so blocking GDF15/GFRAL signalling may worsen the disease and other symptoms." (PMID 32723474, 2020). "It would thus be surprising if GDF-15/GFRAL/RET inhibitors were not simultaneously developed for the treatment of cancer." (PMID 32508832, 2020).
cancer (continued). "Thus, in vitro and in vivo studies suggest that the effects of GDF-15 on cancer cells are manifold, even when no GFRAL-expressing neuronal cells are present." (PMID 32508832, 2020). "For example, altered food intake, reduced adiposity and accompanying changes in systemic metabolism could explain some of the protection from cancer seen in mice with overexpression of GDF15 and would be entirely coherent with GDF15 action via the hindbrain-restricted receptor GFRAL." (PMID 32310257, 2020). "Moreover, it is of interest to determine whether the observed effects in cancer are independent of GFRAL presence." (PMID 39000420, 2024). "If confirmed, this may be a possible explanation for the contradictory growth-promoting effects evidenced in several cancer types, but not in RCC, in which GFRAL presence is decreased and in which GDF-15 rather inhibits progression." (PMID 39000420, 2024). "During cancer, GDF-15 could activate these “non-homeostatic” pathways–specifically acting on the GFRAL-expressing neurons localized in the area postrema and nucleus of the solitary tract—which are able to regulate body weight." (PMID 33396237, 2020).
tumor (25 papers, 2018 to 2025). "In the context of PCa bone metastases, osteocyte-derived GDF15 promotes tumor growth by upregulating early growth response 1 (EGR1) expression through the GFRAL pathway." (PMID 40868185, 2025). "Further research is warranted to clarify aberrant GFRAL expression in tumour tissues and the immunomodulatory effects of the GFRAL antagonists via neural pathways and direct effects on tumour cells, compared to anti-GDF-15 treatment." (PMID 41294666, 2025). "An increased GFRAL expression promotes tumor growth in a dose-dependent fashion with increasing GDF-15 concentration." (PMID 39000420, 2024). "Using both orthotopic and spontaneous models of PDAC, we observe an upregulation of stromal GDF15 and its newly identified receptor tumor-GFRAL expression, as well as MAGEA expression in Gem treated tumors." (PMID 37814317, 2023). "We also investigated an external patient cohort consisting of 28 normal prostate samples, 98 primary tumours, and 13 bone metastases to investigate the levels of GFRAL, the receptor for GDF-15, in prostate tissues." (PMID 37781173, 2023). "The relative expression of the GDF-15 receptor, GFRAL, was higher in metastases compared to benign hyperplasia." (PMID 37781173, 2023). "The levels of GFRAL mRNA expression were significantly higher in metastases and primary tumours compared to the benign hyperplasia group." (PMID 37781173, 2023). "A rat model of cardiac cachexia shows a protective effect of a neutralizing monoclonal anti-GDF-15 antibody, and an antagonistic monoclonal anti-GFRAL antibody prevents RET activation and subsequent weight loss in tumor-bearing mice." (PMID 36361969, 2022). "Similar results were obtained by knocking down GFRAL in tumor cells." (PMID 41035818, 2025). "However, GFRAL is aberrantly expressed in tumour cells and peripheral tissues, suggesting a broader distribution than initially reported." (PMID 41294666, 2025). "Furthermore, the potential paracrine effect of macrophages producing GDF-15 in the tumor microenvironment expressing GFRAL should also be explored." (PMID 39000420, 2024). "This is the only tumor model in which the pathway GDF-15/GFRAL has been demonstrated." (PMID 39000420, 2024). "Moreover, patients whose GC simultaneously expressed RET and GFRAL at a high level had significantly shorter survival time compared to those patients whose tumor tissue expressed both these markers at a low level (474 days vs. 2197 days, P = 0.0002)." (PMID 34149933, 2021). "Importantly, GFRAL knockdown reversed SF-induced chemoresistance and reduced tumor volume." (PMID 41035818, 2025). "Second, GDF15 binds to its receptor GFRAL and activates a chronic inflammatory response via the PI3K/AKT/STAT3 pathway, which induces an imbalance in oxidative stress, resulting in increased tumor burden and drug resistance." (PMID 41035818, 2025). "Thus, the GFRAL- and hepatic triglyceride-dependent tissue-protective effect could also support the survival of neoplastic tissue when attacked by an immune response and thereby change the delicate balance between tumor and immune cells." (PMID 32508832, 2020). "Finally, GFRAL knockdown in tumor cells inhibited GDF15-induced TNF-α and EGF expression, confirming GFRAL as the mediator of GDF15 downstream signaling." (PMID 41035818, 2025). "Notably, knockdown of the GFRAL gene in HNSCC cells significantly reduced the clonogenicity and oxidative stress of tumor cells induced by coculture with CAFs or treatment with CAF supernatant." (PMID 41035818, 2025).
metabolic disease (7 papers, 2020 to 2026). A congenital disorder (due to inherited enzyme abnormality) or acquired (due to failure of a metabolically important organ) disorder resulting from an abnormal metabolic process. "Previous research has demonstrated that GDF-15 affects metabolism and insulin sensitivity by activating GFRAL, suggesting its involvement in metabolic disorders, oxidative stress responses, and inflammation." (PMID 41019919, 2025). "GDF-15 activates GFRAL, influencing metabolism and insulin sensitivity, and may be involved in the development of metabolic disorders, oxidative stress, and inflammation." (PMID 41019919, 2025). "The role of GDF15 and its only known hindbrain-restricted receptor GFRAL has been extensively studied in the past years due to its relevance in the control of energy homeostasis and, thereby, being a potential therapeutic target in the control of metabolic diseases such as obesity." (PMID 39505926, 2024). "Combined, these data may suggest a role of GDF15 in the regulation of survival and aging‐related metabolic diseases through a peripheral mechanism independent of GFRAL." (PMID 32691494, 2020).
neurodegenerative disease (1 paper, 2025). A disorder of the central nervous system characterized by gradual and progressive loss of neural tissue and neurologic function. "GFRAL is a receptor of GDF15 which is implicated in several neurodegenerative diseases and with poor cognitive performance." (PMID 40665476, 2025).
GFRAL also shares sentences with these, for which no sentence is quoted: diabetes (2 papers); eating disorder (2); Insulin resistance (2); pancreatic ductal adenocarcinoma (2); sarcopenia (2); alcohol dependence (1); bladder carcinoma (1); cardiac disease (1); cardiovascular disease (1); cholangiocarcinoma (1); colorectal carcinoma (1); Hepatic steatosis (1); infection (1); lung fibrosis (1); mental disorder (1); mitochondrial disease (1); Nausea (1); non-small cell lung carcinoma (1); oral cancers (1); pancreas carcinoma (1); pancreatitis (1); prediabetes (1); renal clear cell carcinoma (1); Sepsis (1); thyroid cancer (1).